BCL2L10 (BCL2 like 10)
Description:
Promotes cell survival by suppressing apoptosis induced by BAX but not BAK. Increases binding of AHCYL1/IRBIT to ITPR1. Reduces ITPR1-mediated calcium release from the endoplasmic reticulum cooperatively with AHCYL1/IRBIT under normal cellular conditions. Under apoptotic stress conditions, dissociates from ITPR1 and is displaced from mitochondria-associated endoplasmic reticulum membranes, leading to increased Ca(2+) transfer to mitochondria which promotes apoptosis. Required for the correct formation of the microtubule organizing center during oocyte cell division, potentially via regulation of protein abundance and localization of other microtubule organizing center components such as AURKA and TPX2 (By similarity).
Synonyms: Bcl2-L-10; BCL-B; BOO; DIVA
Tractability: Small molecule: a drug acting on it is in phase 2 or 3 trials; a high-quality ligand is known; it belongs to a druggable protein family. Antibody: UniProt predicts a signal peptide or a membrane-spanning region. PROTAC: UniProt records ubiquitination sites on it; ubiquitination databases record sites on it; a small molecule that binds it is known.
Target class: Ion channel; Other ion channel; Bcl-2 family; Miscellaneous ion channel
Gene: Protein-coding gene on chromosome 15 (52,109,263 to 52,112,775, reverse strand). Ensembl gene ENSG00000137875.
Subcellular location: Mitochondrion; Nucleus membrane; Endoplasmic reticulum; Cytoplasm, cytoskeleton, spindle
Gene Ontology:
Molecular function: calcium ion binding; caspase binding; protein binding; channel activity
Biological process: negative regulation of apoptotic process; extrinsic apoptotic signaling pathway in absence of ligand; female gamete generation; intrinsic apoptotic signaling pathway in response to DNA damage; microtubule organizing center organization; positive regulation of apoptotic process; release of cytochrome c from mitochondria; spermatogenesis; regulation of apoptotic process; transmembrane transport
Cellular component: cytosol; endoplasmic reticulum; mitochondria-associated endoplasmic reticulum membrane contact site; mitochondrion; nuclear membrane; membrane; mitochondrial outer membrane; spindle
Genetic constraint (gnomAD): Loss-of-function variants: 16 observed, 11.54 expected, observed/expected ratio (o/e) 1.39, 90% interval 0.93 to 1.89. The synonymous counts are far from expectation, so gnomAD's model fits this gene poorly and the ratio says little. Missense variants: 309 observed, 230.53 expected, observed/expected ratio (o/e) 1.34, 90% interval 1.22 to 1.47. Synonymous variants: 154 observed, 111.46 expected, observed/expected ratio (o/e) 1.38, 90% interval 1.21 to 1.58.
Homologues: Orthologues: chimpanzee BCL2L10 (97% identical), macaque BCL2L10 (86% identical), rabbit BCL2L10 (61% identical), rat Bcl2l10 (44% identical), zebrafish bcl2l10 (17% identical), Caenorhabditis elegans ced-9 (16% identical). Paralogues in human: BOK (21% identical), BAX (19% identical), MCL1 (18% identical), BCL2 (17% identical), BCL2L1 (17% identical), BCL2L2 (15% identical), BAK1 (15% identical), BCL2A1 (14% identical).
Diseases named in the same sentence as BCL2L10 in open-access papers:
BCL2L10 is named in the same sentence as 33 diseases in open-access papers, as found by Europe PMC text mining. Sharing a sentence is not in itself a finding about the gene and the disease. The quoted sentences say what the papers report.
gastric cancer (6 papers, 2011 to 2023). A primary or metastatic malignant neoplasm involving the stomach. "Along this line, the BCL2L10 promoter was found to be aberrantly methylated in gastric cancer, hepatocellular carcinoma, and acute myeloid leukemia." (PMID 33396645, 2020). "The ensuing inhibition of BCL2L10 expression correlated with a decreased overall survival and disease-free survival of hepatocellular carcinoma and gastric cancer patients." (PMID 33396645, 2020). "A previous study investigated the function of the protein BCL2L10 in gastric carcinoma through PI3K-Akt signaling pathway." (PMID 30696802, 2019). "Of note, in gastric cancer cells methylation of the BCL2L10 promoter seems to correlate with decreased expression of BCL2L10 protein level." (PMID 22577154, 2012).
lung carcinoma (5 papers, 2019 to 2025). "Overexpression of Bcl-2 proteins such as Bcl2L10, also referred to as Nrh, is associated with resistance to therapy and poor survival in various cancers, including breast cancer, lung cancer, and leukemia." (PMID 37391438, 2023). "For example, BCL2L10 was found to be overexpressed in breast, prostate, colorectal, and lung cancers, as well as in multiple myeloma, and increased BCL2L10 expression was correlated with poor prognosis 22-25." (PMID 38817872, 2024). "On the other side, BCL2L10 was found to be overexpressed in breast, prostate, colorectal, and lung cancers as well as in multiple myeloma." (PMID 33396645, 2020). "Akin to SVOPL, the lung cancer proapoptotic factor BCL2L10 has been shown to display switching of the most abundantly expressed allele during tumorigenesis." (PMID 31093489, 2019). "The absence of BCL2L10 expression in cell lines from leukemia and from breast, prostate, colorectal, and lung cancers in this study is difficult to reconcile with the later observation that BCL2L10 is overexpressed in all these tumor types." (PMID 33396645, 2020).
melanoma (5 papers, 2020 to 2024). A malignant, usually aggressive tumor composed of atypical, neoplastic melanocytes. "We observed that ABT-737 induced greater cytotoxicity in A375-shBCL2L10 cells compared to A375-scramble cells, confirming that BCL2L10 is implicated in the resistance of melanoma cells to ABT-737." (PMID 33396645, 2020). "For the loss of function approach, we silenced BCL2L10 expression by shRNA in A375, one of the cell lines that expressed the highest levels of endogenous BCL2L10 among the melanoma cell lines tested." (PMID 33396645, 2020). "Based on thisconsideration, we can hypothesize that the increased migration properties observedin melanoma cells overexpressing Bcl2L10 could also be linked tothe reduced [Ca2+]i detected in thesame cells." (PMID 36046354, 2022). "Following our finding that BCL2L10 is implicated in melanoma resistance to cisplatin and ABT-737, we wanted to evaluate whether the effect of BCL2L10 expression in response to these drugs was also observed in the context of simultaneous inhibition of BRAF by the BRAFV600E inhibitor PLX-4032." (PMID 33396645, 2020). "In particular, in accordance withdata demonstrating Bcl2L10 expression in human melanoma cells andmelanoma patient specimens, we confirmed the expression of endogenous Bcl2L10 protein in apanel of melanoma cells." (PMID 36046354, 2022). "We first evaluated the endogenous levels of Bcl2L10 protein in a panel ofestablished and primary human melanoma cells." (PMID 36046354, 2022). "Very recently, Bcl2L10 expression in melanoma tumorspecimens and its role in melanoma response to therapy have beendemonstrated." (PMID 36046354, 2022). "Overexpression of BCL2L10 in melanoma has also been shown to promote cisplatin and ABT-737 resistance." (PMID 36341437, 2022). "The use of a MMPs inhibitor in 3D spheroidinvasion assay reduced invasiveness of melanoma cells overexpressing Bcl2L10protein, pointing out the role of MMPs in mediating Bcl2L10 function." (PMID 36046354, 2022). "In accordance with our previousresults demonstrating the anti-apoptotic activity of Bcl2L10, here we found a decreased[Ca2+]i in melanoma cellsoverexpressing Bcl2L10." (PMID 36046354, 2022). "Here we demonstrated the ability of Bcl2L10 to promote a more aggressive invitro phenotype in melanoma models." (PMID 36046354, 2022). "Overall, data reported in this paper provide evidence supporting a positiverole of Bcl2L10 in melanoma aggressive features." (PMID 36046354, 2022). "In agreement with our recent findings, Bcl2L10 proteinwas expressed in all cells tested, although with different extent, thusconfirming its expression in melanoma cells." (PMID 36046354, 2022). "The expression of BCL2L10 in this study was disparaged since all except one cell line (68 out of the 69, including all 12 from melanoma) presented BCL2L10 levels below the baseline." (PMID 33396645, 2020). "In the present study, we have determined that BCL2L10 is expressed both frequently and at elevated levels in both melanoma cell lines and tissues from melanoma patients." (PMID 33396645, 2020). "Since BCL2L10 was shown to regulate cell proliferation in both ovarian and hepatocellular carcinoma, we first evaluated the impact of altering BCL2L10 level on melanoma cell growth." (PMID 33396645, 2020). "The data presented here allow us to conclude that BCL2L10 is frequently and abundantly expressed in melanoma." (PMID 33396645, 2020). "BCL2L10 is a pro-survival factor in melanoma since its expression reduced the cytotoxic effects of cisplatin, dacarbazine, and ABT-737 (a BCL2, Bcl-xL, and Bcl-w inhibitor)." (PMID 33396645, 2020). "We begin our study by determining the expression of BCL2L10 in a panel of eight melanoma cell lines by Western blot." (PMID 33396645, 2020). "We found that BCL2L10 is expressed in both melanoma cell lines and patients and that its transcription is regulated by STAT3." (PMID 33396645, 2020).
melanoma (continued). "We describe here that BCL2L10 is abundantly and frequently expressed both in melanoma cell lines and tumor samples." (PMID 33396645, 2020). "Our data established that BCL2L10 is a pro-survival protein that contributes to protecting melanoma cells from the DNA-damaging agents cisplatin and dacarbazine." (PMID 33396645, 2020). "We describe that Bcl2l10 is a pro-survival factor in melanoma, being able to protect cells from the cytotoxic effect of different drugs, including cisplatin, dacarbazine, and ABT-737." (PMID 33396645, 2020). "The antibody detected the same two bands (of similar intensity in this case) in M2 melanoma cells stably transfected with BCL2L10-myc." (PMID 33396645, 2020). "One limitation of our study is that the reduced size of our patient cohort prevents us from analyzing changes in BCL2L10 expression in different stages of melanoma." (PMID 33396645, 2020). "We found that BCL2L10 is abundantly and frequently expressed both in melanoma cell lines and tumor samples." (PMID 33396645, 2020). "In this regard, this function of BCL2L10 is similar to that of BCL2, Bcl-xL, and MCL1 since they are both abundantly expressed in melanoma and implicated in cisplatin resistance." (PMID 33396645, 2020). "Meanwhile, both genetic and pharmacological inhibition of BCL2L10 sensitized melanoma cells to cisplatin and ABT-737." (PMID 33396645, 2020). "BCL2L10 plays a pro-survival role by contributing to the resistance of melanoma cells to DNA-damaging agents and ABT-737." (PMID 33396645, 2020). "Inhibition of calcium release fromthe endoplasmic reticulum by Bcl2L10 has been reported as the cause of itsanti-apoptotic activity.Very recently, the ability of Bcl2L10 to protect melanoma cells from the cytotoxiceffect of different drugs has been demonstrated." (PMID 36046354, 2022). "As Bcl2L10 hasbeen reported to exert its antiapoptotic activity in breast cancer modelsthrough inhibition of calcium release from the endoplasmic reticulum, we firstlycharacterized the contribution of Bcl2L10 overexpression tocalcium release in melanoma model." (PMID 36046354, 2022). "Altogether, our results indicate that the elevated expression of BCL2L10 in melanoma contributes to cell survival upon treatment with different cytotoxic compounds, making BCL2L10 a promising target in the context of inhibiting anti-apoptotic Bcl-2 proteins in malignant melanoma treatment." (PMID 33396645, 2020). "Altogether, these findings position BCL2L10 as an important new pro-survival factor in melanoma." (PMID 33396645, 2020). "We describe here for the first time the role of BCL2L10 in melanoma." (PMID 33396645, 2020). "Hence, to study BCL2L10 expression in melanoma patients, we first set to validate this antibody by Western blot and IHC analyses." (PMID 33396645, 2020). "In addition, we determined that BCL2L10 plays a pro-survival role in melanoma, protecting the melanoma cells from different cytotoxic insults." (PMID 33396645, 2020). "In summary, we determined that BCL2L10 is expressed in melanoma and contributes to cell survival." (PMID 33396645, 2020). "These functions were also observed in the context of BRAF inhibition, indicating that targeting BCL2L10 may enhance the clinical efficacy of other therapies against melanoma." (PMID 33396645, 2020). "Moreover, four of the 12 melanoma cell lines were included in our study, and they all showed strong expression of BCL2L10 as assessed by Western blot." (PMID 33396645, 2020). "Antibody #3869 detected the expression of BCL2L10 in all melanoma cell lines analyzed." (PMID 33396645, 2020). "The mechanisms underlying the pro-survival activity of BCL2L10 in melanoma have not been explored in this work." (PMID 33396645, 2020). "Thus, we investigated whether Bcl2L10 was ableto affect in vitro and/or in vivo angiogenesisof melanoma models." (PMID 36046354, 2022). "Hence, targeting BCL2L10 may enhance the clinical efficacy of other therapies for malignant melanoma." (PMID 33396645, 2020).
melanoma (continued). "Since the high frequency of BCL2L10 expression in our cell line collection may be due to a selection process inherent in creating tumor-derived cell lines or the conditions of “in vitro” cell culture, we sought to analyze BCL2L10 expression in melanoma specimens." (PMID 33396645, 2020). "In this study we also observed that the modulation of Bcl2L10 also inducesphosphorylation of ERK1/2, a relevant pathway in melanoma pathobiology." (PMID 36046354, 2022). "The role of BCL2L10, another member of this group, has been poorly studied in cancer and never has been in melanoma." (PMID 33396645, 2020). "This study aimed to investigate the expression and function of BCL2L10 in melanoma since they have not been studied to the present." (PMID 33396645, 2020). "Since BCL2L10 was shown to both promote and inhibit cell death in different systems, to elucidate the role of BCL2L10 in melanoma is not trivial." (PMID 33396645, 2020). "Considering that anti-apoptotic Bcl-2 proteins were and are evaluated as prospective therapeutic targets in melanoma, it is surprising that the role of BCL2L10 in melanoma has never been studied." (PMID 33396645, 2020). "Interestingly, analysis of microarray data generated from A375 melanoma cells treated with siRNAs against 45 transcription factors and signaling molecules (GSE31534) revealed that the silencing of STAT3 markedly reduced BCL2L10 mRNA levels." (PMID 33396645, 2020). "Unlike BCL2L10, which presented a heterogeneous pattern including both nuclear and cytoplasmic localization, P-STAT3 staining was almost exclusively nuclear in the melanoma samples." (PMID 33396645, 2020).
hepatocellular carcinoma (4 papers, 2019 to 2022). A malignant tumor that arises from hepatocytes. "Similarly, in hepatocellular carcinoma samples, methylation of the promoter of BCL2L10 (Bcl-2-like protein 10) was associated with a decreased expression of BCL2L10." (PMID 31861179, 2019). "In ovarian cancer and hepatocellular carcinoma, BCL2L10 acts as a tumor suppressor by negatively regulating cell proliferation." (PMID 33396645, 2020). "Bcl2L10 was found to inhibit angiogenesis of hepatocellular carcinoma invitro and in vivo." (PMID 36046354, 2022). "In addition, forcedexpression of Bcl2L10 in hepatocellular carcinoma model reducedin vitro and in vivo angiogenesis, while we did notobserve significant differences in vitro and invivo angiogenesis assay after Bcl2L10 forcedexpression." (PMID 36046354, 2022). "Bcl2L10 has been also reported to participate in tumorigenicitythrough regulation of invasive/migratory ability of ovarian cancer, as well asangiogenesis and metastatization of hepatocellular carcinoma." (PMID 36046354, 2022). "We found that BCL2L10 expression was low in hepatoma tissues and cells." (PMID 30696802, 2019). "Immunofluorescence assay showed that BCL2L10 and Beclin 1 were co-located in hepatoma cells." (PMID 30696802, 2019). "Overexpression of BCL2L10 decreased the activity of hepatoma cells." (PMID 30696802, 2019). "The Hep3B hepatocellular carcinoma cells were cultured in CM normal medium and EBSS starvation medium for 6 hours and transfected with pcDNA3.1-BCL2L10 or si-BCL2L10 respectively." (PMID 30696802, 2019). "To summarize, in this study, the expression of BCL2L10 and BECN1 in hepatoma cells and their effects on the autophagy of hepatoma cells was observed." (PMID 30696802, 2019). "The aim of this study was to investigate BCL2L10 and BECN1 expression and their effect on autophagy in hepatocellular carcinoma (HCC)." (PMID 30696802, 2019).
acute myeloid leukemia (3 papers, 2017 to 2023). Acute myeloid leukemia (AML) is a group of neoplasms arising from precursor cells committed to the myeloid cell-line differentiation. "Expression of bcl2L10/nrh has been repeatedly reported as a poor prognostic marker, including in acute myeloid leukemia, colorectal cancer and breast cancer." (PMID 37391438, 2023).
breast carcinoma (3 papers, 2022 to 2023). "Bcl2L10, also referred to as Bcl-B or Nrh, was identified as an anti-apoptotic protein, upregulated in various cancers, including leukemia and breast cancer." (PMID 37391438, 2023). "Regarding oncogenic transformation, the team focuses on Nrh, a Bcl-2 homolog also referred to as Bcl2l10 or Bcl-B, which is over-expressed in breast cancer (BC)." (PMID 35883457, 2022). "Bcl2L10 also represents apredictive factor for resistance to azacitidine in myelodysplastic syndromes andacute myeloid leukemia patients, and for response to neoadjuvant chemoradiotherapy in locallyadvanced rectal cancer orto death-inducing agents in breast cancer." (PMID 36046354, 2022).
cervical carcinoma (3 papers, 2019 to 2025). A carcinoma arising from either the exocervical squamous epithelium or the endocervical glandular epithelium. "As for autophagy, BCL2L10 could bind to BECN1 that was an inducer of autophagy at BH1 or BH3 domain, reducing autophagic cell death in cervical cancer by mTor signaling pathway." (PMID 30696802, 2019).
lung adenocarcinoma (3 papers, 2014 to 2025). A carcinoma that arises from the lung and is characterized by the presence of malignant glandular epithelial cells. "ZNF259P1 was significantly correlated with the tumor size of primary lung adenocarcinomas, while ZNF702P was found to be upregulated after BCL2L10 knockdown in two ovarian cell lines." (PMID 37521848, 2022).